MRPS34 (mitochondrial ribosomal protein S34)
Description:
Required for mitochondrial translation, plays a role in maintaining the stability of the small ribosomal subunit and the 12S rRNA that are required for mitoribosome formation.
Synonyms: MRP-S34; MRP-S12; MGC2616; mS34; COXPD32
Tractability: Small molecule: a structure with a bound ligand is known. PROTAC: ubiquitination databases record sites on it; its protein half-life has been measured.
Target class: Other cytosolic protein
Gene: Protein-coding gene on chromosome 16 (1,771,890 to 1,773,158, reverse strand). Ensembl gene ENSG00000074071.
Subcellular location: Mitochondrion
Subcellular location (Human Protein Atlas): Mitochondria
Pathways (Reactome):
Metabolism of proteins: Mitochondrial ribosome-associated quality control; Mitochondrial translation elongation; Mitochondrial translation initiation; Mitochondrial translation termination
Gene Ontology:
Molecular function: structural constituent of ribosome
Biological process: mitochondrial translation
Cellular component: mitochondrion; mitochondrial inner membrane; mitochondrial small ribosomal subunit
Genetic constraint (gnomAD): Loss-of-function variants: 16 observed, 11.5 expected, observed/expected ratio (o/e) 1.39, 90% interval 0.93 to 1.89. The synonymous counts are far from expectation, so gnomAD's model fits this gene poorly and the ratio says little. Missense variants: 419 observed, 277.47 expected, observed/expected ratio (o/e) 1.51, 90% interval 1.39 to 1.64. Synonymous variants: 181 observed, 119.34 expected, observed/expected ratio (o/e) 1.52, 90% interval 1.34 to 1.72.
Gene-disease validity (ClinGen):
ClinGen rates the evidence that MRPS34 causes each of these diseases.
Leigh syndrome (autosomal recessive): Moderate. A progressive neurological disease defined by specific neuropathological features associating brainstem and basal ganglia lesions.
Homologues: Orthologues: chimpanzee MRPS34 (100% identical), macaque MRPS34 (96% identical), mouse Mrps34 (89% identical), pig MRPS34 (84% identical), guinea pig MRPS34 (82% identical), dog MRPS34 (74% identical), tropical clawed frog mrps34 (60% identical), zebrafish mrps34 (59% identical), Caenorhabditis elegans mrps-34 (21% identical), Drosophila melanogaster mRpS34 (19% identical).
Diseases named in the same sentence as MRPS34 in open-access papers:
MRPS34 is named in the same sentence as 12 diseases in open-access papers, as found by Europe PMC text mining. Sharing a sentence is not in itself a finding about the gene and the disease. The quoted sentences say what the papers report.
Leigh syndrome (5 papers, 2019 to 2026). "MRPS34 mutation causes delayed psychomotor development and neurodevelopmental deterioration in Leigh syndrome." (PMID 34763096, 2022). "mS34 (MRPS34)—Four pathogenic mutations in mS34 have been characterized in multiple unrelated individuals affected by Leigh-like or Leigh syndrome." (PMID 33917098, 2021). "Interestingly, biallelic mutations in MRPS34 are known to cause a form of Leigh syndrome, characterized by neurodegeneration in infancy with dystonia and choreoathetoid movements due to basal ganglia dysfunction." (PMID 31123700, 2019). "Biallelic pathogenic variants in MRPS34 cause Combined Oxidative Phosphorylation Deficiency 32 (COXPD32), a rare mitochondrial disorder within the Leigh syndrome spectrum (LSS), ranging from fatal in infancy to adult survival." (PMID 42266416, 2026).
cholangiocarcinoma (2 papers, 2022). A carcinoma that arises from the intrahepatic biliary tree (intrahepatic cholangiocarcinoma) or from the junction, or adjacent to the junction, of the right and left hepatic ducts (hilar cholangiocarcinoma). "It is reported that dysregulated gene expression of MRPS34 was related with cancer cell stemness and chemoresistance in cholangiocarcinoma." (PMID 36304471, 2022). "To determine the role of 4-key-genes in cholangiocarcinoma CSCs, we first knocked down SDHAF2, MRPS34, MRPL11 and COX8A in HCCC9810 cell and overexpressed them in RBE cell, respectively." (PMID 35841118, 2022). "In our study, we demonstrated that CSCs in cholangiocarcinoma have different methionine metabolic features, and 4-key-genes (SDHAF2, MRPS34, MRPL11 and COX8A) could promote ICC stemness in a MAT2A-dependent manner." (PMID 35841118, 2022).
glioblastoma (1 paper, 2021). The most malignant astrocytic tumor (WHO grade IV). "Furthermore, some evidence suggests that several genes expressing MRPs including bS1m (MRPS28), uS2m (MRPS2), uL23m (MRPL23), uS12m (MRPS12), bL12m (MRPL12) and mS34 (MRPS34) may be potential biomarkers for the treatment of glioblastoma with Benzyl isothiocyanate (BITC)." (PMID 34071057, 2021).
liver dysfunction (1 paper, 2015). "The Mrps34 mutation causes tissue-specific molecular changes that result in heterogeneous pathology involving alterations in fractional shortening of the heart and pronounced liver dysfunction that is exacerbated with age." (PMID 25816300, 2015).
mitochondrial disease (2 papers, 2022 to 2024). "Proteomic studies have identified two novel genes related to mitochondrial diseases: MRPS34 and PTCD3." (PMID 39323625, 2024). "Mitochondrial disease-causing mutations were found in thirteen small ribosomal subunit mitoribosomal proteins (MRPS1, MRPS2, MRPS6, MRPS7, MRPS9, MRPS11, MRPS14, MRPS16; MRPS22, MRPS23, MRPS25, MRPS34, MRPS39) and four large ribosomal mitochondrial proteins (MRPL3, MRPL12, MRPL24, MRPL44)." (PMID 36140315, 2022).
infection (1 paper, 2025). The state of being infected such as from the introduction of a foreign agent such as serum, vaccine, antigenic substance or organism. "Associations with M. magneticum and mitochondrial genes like MRPL34 and MRPS34 point to potential microbiome involvement in the host metabolic and apoptotic pathways during early infection stages." (PMID 41417796, 2025).
tumor (1 paper, 2024). "Additionally, studies suggest that high expressions of CYFRA 21-1 and IL-6 in tumor tissue, IL-17 surrounding tumor cells, and the genes SDHAF2, MRPS34, MRPL11, and COX8A in cancer stem cells are associated with a poor prognosis, thus offering novel prognostic avenues for exploration." (PMID 39170710, 2024).
MRPS34 also shares sentences with these, for which no sentence is quoted: breast carcinoma (1 paper); cancer (1); deficiencies (1); Dystonia (1); Q fever (1).